FASN (fatty acid synthase)
Diseases named in the same sentence as FASN in open-access papers (continued):
Sharing a sentence is not in itself a finding about the gene and the disease.
cancer (continued). "Another study in which treatment of cancer cells with the HIV protease inhibitor nelfinavir showed increased SREBP-1 levels correlated with decreased expression of FASN." (PMID 38146334, 2023). "Several studies have reported that advanced cancers exhibit elevated levels of lipogenic enzymes such as fatty acid synthase (FASN)." (PMID 37064140, 2023). "Administration of an FASN inhibitor to obese cancer patients with T2D, NAFLD, and pronounced leptin insufficiency, however, should take into account the possibility of an induced deterioration of glycemic control and liver function." (PMID 37681411, 2023). "Here, we provide an overview of the involvement of the pro-oncogenic enzyme in the hallmarks of cancer making FASN a promising target in anti-cancer therapy to circumvent resistance to chemotherapies." (PMID 36934087, 2023). "The expression of fatty acid synthase is enhanced through the induction of epithelial mesenchymal transition (EMT) in the metastasis of a certain cancer cell type." (PMID 37367867, 2023). "FASN inhibitors, such as the anti-obesity drug Orlistat, have shown significant anti-tumor effects in various cancers." (PMID 37700339, 2023). "De novo synthesis of FA (16:0) is enhanced by increased expression of fatty acid synthase (FASN) in various cancers." (PMID 36707819, 2023). "The ability of FASN inhibition to suppress cancer cell growth was also proven in a cell line of a pediatric malignant rhabdoid kidney tumor." (PMID 36834678, 2023). "In turn, HER1/2 induce expression of FASN via activation of the MAPK and PI3K/Akt pathways highlighting a positive feedback to maintain high levels of FASN in cancer cells." (PMID 36934087, 2023). "Cancer cells were discovered to promote resistance by overexpressing the FASN enzyme when they were treated with gemcitabine." (PMID 37110218, 2023). "TVB2640, a FASN inhibitor, has been observed to have a significant inhibitory effect on tumor growth in cancer cell lines and xenograft models, but due to its pharmacological nature, its clinical transformation and application are limited." (PMID 38189049, 2023). "A number of studies have investigated the potential of inhibitors of fatty acid synthase as a potential therapy in cancer." (PMID 37108548, 2023). "FASN has been identified as an oncogene in gliomas and cancers of the breast, colon, prostate, lung, skin, and bladder." (PMID 37046804, 2023). "Multiple oncogenic signaling cascades (EGFR, CXCR4, FASN, P-gp, β-catenin, GSK-3B, STAT1, JAK2, MUC1, etc) are hallmarks of cancer cells that are associated with drug resistance, tumorigenic potential, and metastasis." (PMID 37151801, 2023). "Because it provides a large amount of energy for the proliferation of malignant tumors, FASN, as the hub of lipid metabolism, plays an increasingly prominent role in tumors with lipid-rich phenotypes." (PMID 37056351, 2023). "Inhibiting FASN forces cancer cells to switch towards lipid uptake, which are enriched in ROS labile PUFA, which we exploit by the addition of a ROS elevating drug." (PMID 37072838, 2023). "This analysis showed that UM is within the top five of cancers expressing high levels of FASN and SREBP1." (PMID 37444561, 2023). "Inhibiting the FASN through RNA silencing as well as chemical inhibitor reverses the resistance of cancer cells against Herceptin." (PMID 37256177, 2023). "To date, attempts of pharmacologically targeting FASN have been challenged by severe toxicity and compensatory mechanisms activated by cancer cells, namely upregulation of FA uptake." (PMID 36675307, 2023). "Cancer cells exploit two mechanisms for acquiring fatty acids: de novo lipogenesis via fatty acid synthase and cytosolic acetyl‐CoA (primarily derived from metabolites that yield cytosolic citrate), and from extracellular lipolysis." (PMID 36652113, 2023). "Multiple reports have shown that inhibition of FASN leads to decreased cancer cell growth and tumor growth." (PMID 38069382, 2023).
cancer (continued). "Significantly, ACC and FASN all exhibited stronger expression in the cancer region than adjacent normal region, which were highly consistent with the spatial characteristics of palmitic acid." (PMID 37120513, 2023). "One such example is the (Fatty Acid Synthase) FASN enzyme which is highly expressed in cancer cells and is also considered to be a marker for poor prognosis of cancer." (PMID 36816957, 2023). "For example, up-regulated fatty acid synthase (which catalyzes palmitate synthesis) in cancer has been identified as a therapeutic target." (PMID 37777749, 2023). "The changes in FASN activity are thought to be the stress response of cancer cells reacting to changes in cellular micro-environments." (PMID 38003694, 2023). "The overarching goal of our study is the design of a potential novel therapeutic strategy for advanced HER2+ GC, for instance, by cotargeting HER2 and FASN oncogenic/metabolic axis to eradicate both the root of cancer and the bulk of the tumor mass." (PMID 36753044, 2023). "FASN activity in cancer cells is responsible for the accumulation of fatty acids in the TME, which are detrimental for DC ability to present antigens." (PMID 37180110, 2023). "Cancer cells secrete M-CSF that promotes fatty acid synthase (FASN) activity in myeloid cells, including TAMs." (PMID 37275901, 2023). "To determine if the increase in lipogenesis is important to Cr(VI)-transformed cell survival and cancer properties, we examined soft agar colony formation, proliferation, and tumor growth after drug inhibition (C75) of FASN." (PMID 38069382, 2023). "Metformin leads to reprograming of lipid metabolism, as a hallmark of cancer, by increase in acetyl-CoA carboxylase (ACC) and fatty acid synthase (FASN), and miRNA regulation." (PMID 36849958, 2023). "Further developing compounds that promote FBXW7β-mediated FASN degradation or inhibit CSN6/FASN activity can be further developed as a therapeutic design for CSN6-overexpressing cancers." (PMID 37202390, 2023). "Since FASN has been demonstrated to intertwine with various signaling networks to initiate carcinogenesis and accelerate cancer progression, FASN has been widely considered as a tumor therapeutic target." (PMID 37587470, 2023). "It was reported that C75 inhibition in A549 cells inhibited FASN and cancer properties of these cells; our data match these results." (PMID 38069382, 2023). "Our studies of the role of EGF/CSN6 in hindering FBXW7β-mediated FASN ubiquitination reveal rational therapy for cancer intervention." (PMID 37202390, 2023). "FASN is an important multi-enzyme protein that regulates fatty acid biosynthesis (de novo lipogenesis) in cancer cells and provides fatty acids as a source of energy to the proliferating cells." (PMID 37705114, 2023). "Compared to normal human tissues, increased FASN expression promotes endogenous FA synthesis in various cancer tissues." (PMID 38189049, 2023). "Inhibition of ACC and FASN has also been shown to modulate cancer cell responses to MT-targeting drugs, including taxol and nocodazole." (PMID 36617578, 2023). "CSN6 antagonizes cytosolic FBXW7β’s activity by enhancing FBXW7β autoubiquitination and degradation, thereby preventing FBXW7β/GSK3β-mediated FASN ubiquitination and degradation, lending support to why both CSN6 and FASN are positively correlated in cancer." (PMID 37202390, 2023). "Results showed that FASN expression and tumor purity were positively correlated in most cancers, while the infiltration scores of T cells and B cells were negatively associated with FASN expression." (PMID 37696831, 2023). "FASN is the most targetable among lipogenesis genes due to its high degree of overexpression in cancer cells." (PMID 35742953, 2022). "Promising therapeutic results seem to be rooted in distinct FASN tissue distribution and activity between normal and cancer tissue, suggesting FASN as a potential biomarker and advancing FASN as target of currently ongoing clinical trials." (PMID 35323656, 2022).
cancer (continued). "Currently, fatty acid synthesis inhibitors (FAS), especially targeting fatty acid synthase (FASN), have been focused on as potential strategies for cancer treatment." (PMID 36300115, 2022). "FASN is crucial for governing the activity of tumor immune cells; however, its role in pan-cancer and its correlation with tumor immunity have rarely been reported." (PMID 36555243, 2022). "As C16:0 is the main product of FASN, cancer cells commonly co-overexpress FASN and SCD to maintain homeostatic levels of SFAs and MUFAs." (PMID 34983949, 2022). "It has also been reported that diallyl sulfide (DAS) mediated modulation of FASN leads to cancer cell death in Benzoapyrene-induced lung carcinogenesis." (PMID 35791446, 2022). "C75 is a synthetic FASN inhibitor found to exert antitumour effects in breast, ovarian and endometrial cancer." (PMID 35448537, 2022). "Our findings and these studies identify a novel mechanism of FASN in cancer lipid metabolism, providing more possibilities for future investigation." (PMID 35597782, 2022). "Both SRPK2 and FASN are overexpressed in numerous cancers, suggesting potential therapeutic potential." (PMID 36096767, 2022). "Taking into account its multifaceted roles in FA metabolism and oncogenic processes, multiple FASN inhibitions were developed for cancer treatment, such as first-generation and next-generation agents." (PMID 36428733, 2022). "FASN regulates fatty acid metabolism and plays a critical role in the growth and tissue invasion by many cancers." (PMID 36516496, 2022). "For instance, miR-873-5p promoted CC development via downregulating ZEB1 and miR-497-5p acted as an anti-cancer molecule by targeting Fatty Acid Synthase (FASN) in CC." (PMID 35609310, 2022). "To further investigate the relationship between FASN expression and tumor prognosis, we employed Sangerbox3.0 to examine FASN expression for overall survival in 44 cancer types and disease-free interval in 32 cancer types." (PMID 36555243, 2022). "New FASN inhibitors with less in-vivo toxicity like TVB-3166 exhibited potent anti-tumor effects in chemoresistant cancer cells." (PMID 35646898, 2022). "Selectively targeting FASN and lipogenesis have been reported to induce caspase-dependent apoptosis in cancers." (PMID 36362924, 2022). "Reports have shown a positive correlation for FASN protein expression during the progression of different cancers such as stomach, lung, breast, prostate, colon, and ovarian carcinomas." (PMID 35879772, 2022). "The cancer cells disseminated in these white adipose tissues express FASN, which is a marker of lipid metabolism, and CD36, which is a transporter of extrinsic fatty acids." (PMID 36434071, 2022). "Consistently, low respiration and glycolytic capacity were observed when FASN was deleted in MEFs infected with retroviral particles expressing the PyMT breast cancer oncogene (FASN∆/∆-PyMT) as compared to control FASNlox/lox-PyMT MEFs." (PMID 35742953, 2022). "Unfortunately, most of the FASN inhibitors have good anti-cancer effects, but the side effects hinder thier advancement in clinical trials." (PMID 39086974, 2022). "Fatty acid synthase is a key enzyme involved in fatty acid synthesis and is highly expressed in numerous cancers." (PMID 35743814, 2022). "According to our findings, immune infiltration was significantly negatively correlated with FASN expression in up to 35 (totaling 44) cancers." (PMID 36555243, 2022). "Compared to the parental cancer cells, FASN, SCD1 and FADS2 expression at the mRNA and protein level consistently downregulated in the GFPT1 and OGT knockdown cells." (PMID 35844792, 2022). "This molecule was demonstrated to inhibit FASN in a xenograft model of NSCLC cancer, significantly reducing tumor growth." (PMID 35159223, 2022). "AS a druggable target for cancer treatment, FASN has shown efficacy in diverse tumors, and its relevant metabolic treatments have broad prospects." (PMID 36172157, 2022).
cancer (continued). "Given these roles of endogenous fatty acid synthesis in cancer progression, FASN is an attractive target for cancer therapy." (PMID 34983949, 2022). "In this study, we comprehensively examined the expression, prognostic significance, and promoter methylation of FASN, and its correlation with immune cell infiltration in pan-cancer." (PMID 36555243, 2022). "Several fatty acid synthase (FASN) inhibitors, including antifungal agent cerulenin, its synthetic derivative C75, and triclosan have been shown to inhibit cancer cell growth by inducing cell death." (PMID 35225948, 2022). "Correlations common to control and OC were between β-HAD and FATP4 (control: p = 0.011, r = 0.666; cancer: p = 0.003, r = 0.546) and FASN and GLUT1 (control: p = 0.001, r = 0.824; cancer: p = 0.002, r = 0.563)." (PMID 36012230, 2022). "Yellen and Foster suggested a feedback activation of Akt and ERK in K‐Ras‐driven cancer cells in response to FASN inhibition." (PMID 35243817, 2022). "High-performance liquid chromatography-tandem mass spectrometry showed that SFN regulates the expression of lipoproteins; highly expressed FASN (fatty acid synthase) correlates with cancer malignancy and poor prognosis." (PMID 40396015, 2022). "Fatty acid synthase (FASN) is a key enzyme for the synthesis of long-chain fatty acids from malonyl-CoA, and FASN overexpression has been identified in many cancer types." (PMID 36092874, 2022). "This formation occurs by lipogenic enzymes which are highly expressed in cancer cells and include acetyl-CoA carboxylase, fatty acid synthase, and ATP citrate lyase." (PMID 35634242, 2022). "FASN overexpression in cancers had frequently been related to biological aggressiveness and a poor prognosis." (PMID 35401213, 2022). "FASN was reported as highly upregulated in BC cell lines, including the hormone-dependent MCF7 line, and in a variety of human cancers in association with invasion and poor prognosis." (PMID 36500393, 2022). "It has been reported that FASN plays a substantial role in normal cells and is involved in tumor progression by regulating energy metabolism, which is a possible target for cancer therapy." (PMID 36555243, 2022). "FASN is needed in cancer cells for synthesis of fatty acids, which in turn are used for energy production, cellular membranes, signaling molecules, and membrane protein anchors." (PMID 36558071, 2022). "The disruption of lipid rafts by FASN inhibition impairs signal transduction pathways, leading to the promotion of cancer cell apoptosis." (PMID 35243817, 2022). "The expression level of fatty acid synthase in cancer cells was significantly higher than that in normal cells." (PMID 36431859, 2022). "In this light, different mechanisms, including overexpression of fatty acid synthase to protect cancer cells from apoptosis and lipogenesis as a support for cancer cell proliferation, have been discussed in several cancer types." (PMID 36355141, 2022). "Ole functions as an anti-cancer agent by having anti-proliferative, anti-angiogenic and apoptotic, antioxidant, fatty acid synthase inhibiting, cytoskeleton disrupting, and anti-inflammatory properties." (PMID 36013319, 2022). "FASN expression is upregulated in several types of cancer and correlates with poor prognosis, such as colorectal cancer, endometrial carcinoma, mantle cell lymphoma, B-cell non-Hodgkin lymphoma, multiple myeloma, ovarian cancer, breast cancer, and PCa." (PMID 36358940, 2022). "Together, the data further confirm the specificity of TVB inhibitors in targeting FASN in cancer cells." (PMID 35742953, 2022). "A proto-oncogenic transcription factor, FBI-1 can directly interact with SREBP-1 via DNA-binding domains to synergistically activate FASN transcription for maintaining rapid cancer cell proliferation." (PMID 35912181, 2022).
cancer (continued). "Here, we investigated the relationship between FASN expression and DNA methylation in human tumors for the first time and found that the promoter of FASN is hypomethylated in almost all cancer types, while the gene body is hypermethylated." (PMID 36555243, 2022). "This study further emphasizes the potential importance of utilizing FASN as a therapeutic target for the prevention and treatment of early stages of cancer." (PMID 35742953, 2022). "Fatty acid synthesis is another key contributor to the lipid supply of malignant cells, with many cancers exhibiting increased expression of many lipogenic enzymes, including fatty acid synthase (FAS)." (PMID 35631131, 2022). "We further examined eleven cancer-type DNase-seq data from ENCODE and discovered that they were significantly enriched in FASN promoters." (PMID 36555243, 2022). "This can be achieved by initiating de novo FA synthesis, normally a function of adipocytes and hepatocytes but an acquired characteristic of cancer cells driven by elevated FA synthase (FASN) expression." (PMID 35732120, 2022). "In contrast, the viability of cancer cells notably decreases when they are treated with FASN inhibitors such as triclosan and orlistat." (PMID 35790992, 2022). "FASN, like cancer cells, is a major enzyme in FA production in M1 macrophages, and it is primarily regulated by SREBPs." (PMID 36816174, 2022). "FASN is overexpressed in many forms of cancer, and increased FASN expression and activity confer a survival advantage in cancer cells." (PMID 36358687, 2022). "Aberrant lipid synthesis via upregulation of FASN is crucial for cancer cells, and targeting FASN can be a potential therapeutic strategy in many cancers, including CRC." (PMID 35742953, 2022). "Key regulatory factors and enzymes of lipogenesis include SREBPs, acetyl coenzyme A carboxylase (ACC), ACLY and fatty acid synthase (FASN), all of which are up-regulated to varying degrees in human cancers." (PMID 36038892, 2022). "So far, the role of the ACC inhibitor and its impact on the pro-carcinogenic activity of oestradiol has received little attention, probably stemming from the focus on FASN instead of ACC as the key enzyme to target FA synthesis in cancer." (PMID 35448537, 2022). "Based on analysis of the TAGA, GSE13507, GSE3167, and GSE40355 datasets, FASN was differentially expressed between cancer and normal tissue." (PMID 35392075, 2022). "Multiple FASN inhibitors, including C75, Cerulenin, and orlistat, have shown antitumor activity in cancer cell lines or mouse models." (PMID 35597782, 2022). "Overall, FASN was significantly increased in twenty-three (total thirty-four) cancer types and was markedly decreased in five cancer types based on the TCGA and GTEx data." (PMID 36555243, 2022). "First-generation FASN inhibitors, such as C75, orlistat, and cerulenin, successfully reduced cancer cell growth in preclinical models." (PMID 36358940, 2022). "FASN expression and subsequent palmitate production can lead to cancer progression through multiple mechanisms including providing substrates for protein palmitoylation, lipid droplet formation, phospholipid synthesis, or β-oxidation." (PMID 36096767, 2022). "Previously, we believed that the SREBP1/FASN signaling pathway controls fatty acid synthesis in various cancers." (PMID 35743814, 2022). "Some recent studies have demonstrated that aberrant activation of FASN can impair the anti-tumor immunity in cancer immunotherapy." (PMID 35216285, 2022). "We therefore also analyzed immune cell infiltration, immune function, immune microenvironment, and immune checkpoints, to explore the role of FASN in cancer immune infiltration and responses." (PMID 35392075, 2022). "FASN over-expression can be detected in cancers such as ovarian cancer, pancreatic cancer, and non-small cell lung cancer." (PMID 35743814, 2022). "Previous studies have reported that orlistat exerts growth-inhibitory effects against various cancers by inhibiting FASN." (PMID 35216285, 2022).